NDUFB3 (NADH:ubiquinone oxidoreductase subunit B3)
Description:
Accessory subunit of the mitochondrial membrane respiratory chain NADH dehydrogenase (Complex I), that is believed not to be involved in catalysis. Complex I functions in the transfer of electrons from NADH to the respiratory chain. The immediate electron acceptor for the enzyme is believed to be ubiquinone.
Synonyms: CI-B12; B12; MC1DN25
Tractability: Small molecule: an approved drug acts on it; a structure with a bound ligand is known. Antibody: UniProt predicts a signal peptide or a membrane-spanning region. PROTAC: ubiquitination databases record sites on it; its protein half-life has been measured.
Gene: Protein-coding gene on chromosome 2 (201,071,433 to 201,085,754, forward strand). Ensembl gene ENSG00000119013.
Subcellular location: Mitochondrion inner membrane
Pathways (Reactome):
Metabolism: Complex I biogenesis; Respiratory electron transport
Gene Ontology:
Molecular function: NADH dehydrogenase (ubiquinone) activity
Biological process: aerobic respiration; mitochondrial electron transport, NADH to ubiquinone; proton motive force-driven mitochondrial ATP synthesis; electron transport chain; proton transmembrane transport
Cellular component: mitochondrial inner membrane; mitochondrion; respiratory chain complex I
Genetic constraint (gnomAD): Loss-of-function variants: 8 observed, 9.84 expected, observed/expected ratio (o/e) 0.81, 90% interval 0.48 to 1.46. That is too few expected variants to judge how well the gene tolerates losing a copy. Missense variants: 93 observed, 116.91 expected, observed/expected ratio (o/e) 0.8, 90% interval 0.67 to 0.94. Synonymous variants: 29 observed, 38.92 expected, observed/expected ratio (o/e) 0.75, 90% interval 0.55 to 1.02.
Gene-disease validity (ClinGen):
ClinGen rates the evidence that NDUFB3 causes each of these diseases.
mitochondrial disease (autosomal recessive): Definitive.
Homologues: Orthologues: chimpanzee NDUFB3 (100% identical), macaque NDUFB3 (95% identical), rabbit NDUFB3 (84% identical), dog NDUFB3 (82% identical), guinea pig NDUFB3 (81% identical), mouse Ndufb3 (78% identical), rat Ndufb3 (76% identical), rat AABR07060996.1 (73% identical), rat Ndufb3l3 (72% identical), zebrafish ndufb3 (59% identical), Drosophila melanogaster ND-B12 (36% identical), Caenorhabditis elegans ndub-3 (27% identical).
Diseases named in the same sentence as NDUFB3 in open-access papers:
NDUFB3 is named in the same sentence as 29 diseases in open-access papers, as found by Europe PMC text mining. Sharing a sentence is not in itself a finding about the gene and the disease. The quoted sentences say what the papers report.
Huntington disease (4 papers, 2012 to 2026). Huntington disease (HD) is a rare neurodegenerative disorder of the central nervous system characterized by unwanted choreatic movements, behavioral and psychiatric disturbances and dementia. "Studies in recent years have shown that NDUFB3 is a key protein involved in the oxidation of phosphate and is involved in Parkinson’s disease, Huntington’s disease, and Alzheimer’s disease pathways." (PMID 36357826, 2022). "Furthermore, the transcription factor A, several NADH-ubiquinone oxidoreductases (Ndufa3, Ndufb3) were involved in AD and Huntington’s disease (HD)." (PMID 40545497, 2025). "For example: Huntington’s disease (NDUFA7, NDUFC1, NDUFB2, NDUFB3, NDUFA8), atrophy of optic nerve (NDUFS4) and Leigh syndrome (NDUFS7, NDUFA2, NDUFS4)." (PMID 23028713, 2012). "In addition, COX7B, NDUFB3, and UQCRQ were both primarily enriched in some pathways, such as ribosome, Huntington disease, oxidative phosphorylation, Alzheimer disease, and Parkinson disease." (PMID 41517693, 2026).
lactic acidosis (2 papers, 2016 to 2020). Metabolic acidosis characterized by the accumulation of lactate in the body. "Our previous report of NDUFB3 mutations manifesting as SS, with a relatively benign clinical course compared with the life-threatening lactic acidosis, which can result, provides a similar example of mild metabolic phenotype presenting with SS-UA." (PMID 32939436, 2020).
Sepsis (2 papers, 2023 to 2024). Sepsis is defined as life-threatening organ dysfunction caused by a dysregulated host response to infection. "After the verification of high expression of NDUFB3 with our sepsis clinical specimens, the effect of NDUFB3 on mitochondria was tested with a confocal microscope." (PMID 37228596, 2023). "The expression of NDUFB3 was inhibited by small interfering RNA technology and the mitochondrial function was significantly reduced in the sepsis model." (PMID 37228596, 2023). "Overall, our results suggested that NDUFB3 is highly expressed in sepsis and plays a vital role in the mitochondrial quality imbalance in LPS -treated H9C2 cells." (PMID 37228596, 2023). "The results of qPCR showed that the expression of NDUFB3 was higher in sepsis, whereas the expression of LETMD1 and BCKDHB were lower in SP than in HC." (PMID 37228596, 2023). "In vitro experiments showed NDUFB3 plays an important role in the process of mitochondrial mass imbalance in the LPS-simulated sepsis model." (PMID 37228596, 2023). "By qPCR, the high expression of NDUFB3 in sepsis was verified by our clinical specimens." (PMID 37228596, 2023). "NDUFB3 (NADH dehydrogenase (ubiquinone) 1 beta subcomplex, 3) is an important subunit of mitochondrial respiratory complex I. Our data showed NDUFB3 played an important role in the process of mitochondrial mass imbalance in the simulated sepsis model treated with LPS." (PMID 37228596, 2023).
thyroid cancer (2 papers, 2022 to 2024). "Given the critical role of NDUFB3 in mitoROS and thyroid cancer clinicopathology, we sought to investigate the possible signaling pathway caused by its differential expression in thyroid cancers." (PMID 35087620, 2022). "The next two groups were selected based on the NDUFB3 expression levels from the 510 thyroid cancer samples in TCGA cohort: higher (top 25%) and lower (bottom 25%) expression." (PMID 35087620, 2022). "The expression of mitoROS regulators represented by NDUFB3 was associated with the clinical features and PFS of patients with thyroid cancers." (PMID 35087620, 2022). "Our study showed that a prosurvival function following NDUFB3 overexpression in thyroid cancer cell-derived xenograft tumors can be observed." (PMID 35087620, 2022). "Consequently, we attempted to preliminarily investigate the connections between NDUFB3 expression and mitoROS levels, as well as clinicopathological features in thyroid cancer." (PMID 35087620, 2022). "The mitoSOX assay confirmed diminished mitoROS generation in NDUFB3 knockdown thyroid cancer cells." (PMID 35087620, 2022). "This revealed that the NDUFB3-expressing population represented the population of mitoROS regulators in thyroid cancers, and that its expression may be positively correlated with mitoROS levels." (PMID 35087620, 2022). "Thus, we infected thyroid cancer cells with lentivirus encoding a human NDFUB3 cDNA or a control noncoding lentivirus and confirmed the overexpression of NDUFB3 using western blotting." (PMID 35087620, 2022). "Together, these findings uncovered an important clue that increasing mitoROS levels by sideroxylin treatment or NDUFB3 overexpression could effectively suppress thyroid cancer growth." (PMID 35087620, 2022).
anaplastic thyroid cancer (1 paper, 2022). "We performed lentivirus-mediated shRNA knockdown targeting human NDUFB3 in both BCPAP (papillary thyroid cancer cells) and C643 (anaplastic thyroid cancer cells) cell lines." (PMID 35087620, 2022).
glaucoma (1 paper, 2023). Increased pressure in the eyeball due to obstruction of the outflow of aqueous humor. "Both MRPL50 and NDUFB3 have been implicated in AD, glaucoma, and age-related neurodegeneration." (PMID 37834458, 2023).
glioblastoma (1 paper, 2023). The most malignant astrocytic tumor (WHO grade IV). "This is consistent with a previous report that showed that GO attenuates the expression of genes associated with the oxidative phosphorylation complexes, such as NDUFA1, NDUFB3, and NDUFS4 in glioblastoma U87 cell line." (PMID 36839713, 2023).
nasopharyngeal carcinoma (1 paper, 2022). A carcinoma arising from the nasopharyngeal epithelium. "However, in the field of tumor pathology, NDUFB3 has only been associated with nasopharyngeal carcinoma." (PMID 35087620, 2022). "In vitro knockdown of NDUFB3 in nasopharyngeal carcinoma cells exhibited significant reductions in cisplatin-induced mitoROS production, demonstrating that it positively correlated with mitoROS production consistent with our results." (PMID 35087620, 2022).
nonalcoholic steatohepatitis (1 paper, 2022). "NDUFB3 homozygous pathogenic variant was also found in a patient with a mitochondrial disorder and with a prior diagnosis of nonalcoholic steatohepatitis." (PMID 35087620, 2022).
rheumatoid arthritis (1 paper, 2024). A chronic, systemic autoimmune disorder characterized by inflammation in the synovial membranes and articular surfaces. "Finally, we found through qRT-PCR experimental analysis that NDUFB3, NGLY1, and SLC25A4 are highly expressed in rheumatoid arthritis compared with normal tissues." (PMID 39421742, 2024).
Stroke (1 paper, 2024). Sudden impairment of blood flow to a part of the brain due to occlusion or rupture of an artery to the brain. "The main finding of this study is that the COX6C and NDUFB3 genes are highly expressed in septic shock and stroke, and the higher the expression of these genes, the worse the prognosis." (PMID 39655053, 2024). "The significant roles of COX6C and NDUFB3 genes in septic shock and stroke will be validated using public datasets." (PMID 39655053, 2024). "COX6C and NDUFB3 genes are highly expressed in septic shock and stroke." (PMID 39655053, 2024). "However, the relationship between COX6C, NDUFB3 genes and septic shock and stroke is currently unclear." (PMID 39655053, 2024). "COX6C and NDUFB3 are highly expressed in septic shock and stroke, and may play a significant role in the development of septic shock and stroke through cellular regulation and other pathways." (PMID 39655053, 2024). "COX6C and NDUFB3 may serve as molecular targets for precise treatment of septic shock and stroke, providing a certain direction for the mechanism research of septic shock and stroke." (PMID 39655053, 2024). "Therefore, it is speculated that COX6C and NDUFB3 genes play an important role in the process of ischemia–hypoxia, neuronal apoptosis, and neuroinflammatory response in stroke." (PMID 39655053, 2024). "Core genes (UQCRQ, USMG5 [ATP5MD], COX6C, NDUFB3, ATP5L [ATP5MG], COX7C, NDUFA1, NDUFA4) were highly expressed in septic shock and stroke samples." (PMID 39655053, 2024).
cancer (5 papers, 2015 to 2025). A tumor composed of atypical neoplastic, often pleomorphic cells that invade other tissues. "Because previous reports suggest that NDUFB3 is critical for the complex I assembly, regulates associated ROS production, and is associated with cancer development, we performed further investigation on NDUFB3." (PMID 38437062, 2024). "The remaining eight target genes (CFL1, FNBP4, NDUFB3, OCIAD2, PLIN3, POU2AF1, RAC1, TMEM141) presented a combined influence in five or fewer cancer types." (PMID 39201394, 2024).
tumor (4 papers, 2019 to 2024). "Seahorse curves showed that the basal and maximum oxygen consumption rates (OCRs) were increased in the NDUFB3-overexpressed tumor cells." (PMID 35087620, 2022). "Consistent with the in vitro experiment, ex vivo mitoSOX staining of these tumor cells showed a diminished mitoROS level in NDUFB3 knockdown tumor cells." (PMID 35087620, 2022). "In contrast, when the tumor cells with NDUFB3 knockdown were inoculated in mice, significantly accelerated tumor growth and shortened survival times were observed compared to mice in the empty vector group." (PMID 35087620, 2022). "NDUFB3 overexpression and treatment with sideroxylin effectively increased mitoROS and limited in vivo tumor growth." (PMID 35087620, 2022). "In a mouse xenograft model, the tumor volumes in the NDUFB3-overexpressed tumor cells were delayed for approximately 10 days." (PMID 35087620, 2022). "The in vivo NDUFB3 overexpression and sideroxylin treatment significantly suppressed tumor growth and prolonged survival, concurrently elevating mitoROS levels ex vivo in mouse xenograft models." (PMID 35087620, 2022). "Our data uncovered that NDUFB3 overexpression reduced tumor sizes and weights." (PMID 38437062, 2024). "The overexpression of NDUFB3 in tumor tissues was confirmed by immunohistochemistry." (PMID 38437062, 2024). "Results showed that NDUFB3 overexpression significantly decreased the tumor volumes." (PMID 38437062, 2024). "Next, we assessed whether there was a mitoROS inducer that specifically augmented mitoROS production could diminish tumor growth and showcase an inhibitory effect on tumor growth that exceeded NDUFB3 overexpression." (PMID 35087620, 2022). "We subsequently hypothesized that NDUFB3 overexpression would be capable of slowing tumor growth in vivo." (PMID 35087620, 2022). "Because it had been proposed that NDUFB3 was a critical step in early complex I assembly and regulated associated ROS production, we reasoned that NDUFB3 downregulation helped maintain ROS balance in HCC cells by keeping complex I activity at appropriate levels, thereby promoting tumor progression." (PMID 38437062, 2024). "Together, these data confirmed the relationship between low NDUFB3 expression and its association with a higher percentage of advanced TNM stage, as well as highlight the negative regulatory role of NDUFB3 in tumor growth and the potential involvement of mitoROS in NDUFB3-modulated tumor growth." (PMID 35087620, 2022).
infection (2 papers, 2019 to 2021). The state of being infected such as from the introduction of a foreign agent such as serum, vaccine, antigenic substance or organism. "The infection efficiency of NDUFB3-overexpressed adenovirus was verified." (PMID 33618676, 2021).
neurodegenerative disease (2 papers, 2025 to 2026). A disorder of the central nervous system characterized by gradual and progressive loss of neural tissue and neurologic function. "In a TBI rat model, Ndufa3, Ndufb3, and other subunits were identified among the genes correlated with neurodegenerative diseases." (PMID 40545497, 2025).
metabolic disorders (1 paper, 2024). "It is therefore speculated that the COX6C and NDUFB3 genes may play an important role in the inflammatory response, oxidative stress, and metabolic disorders in septic shock." (PMID 39655053, 2024).
neurological disorder (1 paper, 2015). "However, as a note of interest, these CNVs included the NDUFB3, NIF3L1, PPEF2, CACNA2D1 and GPC5 genes, which are expressed in the brain and/or have been implicated in neurological disorder." (PMID 25585696, 2015).
NDUFB3 also shares sentences with these, for which no sentence is quoted: Alzheimer disease (3 papers); Parkinson disease (3); COVID-19 (2); Cerebral ischemia (1); diabetes (1); fibrosis (1); hematological disease (1); Leigh syndrome (1); melanoma (1); mitochondrial disease (1); papillary thyroid cancer (1); thyroid tumor (1).